EGF (epidermal growth factor)
Diseases named in the same sentence as EGF in open-access papers (continued):
Sharing a sentence is not in itself a finding about the gene and the disease.
adenocarcinoma (24 papers, 2007 to 2025). A common cancer characterized by the presence of malignant glandular cells. "EGF-stimulated initial protrusion in MTLn3 rat adenocarcinoma cells is caused by cofilin activation and severing of F-actin, which is coincident with actin polymerization and formation of lamellipodia." (PMID 19008941, 2008). "Importantly, the L858R mutation in EGFR is frequently found in human adenocarcinoma and is known to confer ligand-independent EGF signaling." (PMID 23285300, 2012). "This study aims to identify two representative EGF gene loci through predictive modeling methods and analyze their distribution in young adenocarcinoma patients." (PMID 40696566, 2025). "Patients bearing squamous-cell or adenocarcinomas and serum EGF concentration above 870 pg/ml had better survival compared to control patients treated with best supportive care as maintenance, confirming tumors’ sensitivity to the EGF depletion." (PMID 34211836, 2021). "To pursue this, we micro-dissected and dissociated adenocarcinomas from Lin28bLo/Let7IEC-KO mice and cultured “tumoroids” from these lesions in medium supplemented with EGF, Noggin, and Rspo1 for enteroid culture." (PMID 26244988, 2015). "In metastatic MTLn3mammary adenocarcinoma cells stimulation with EGF results in extensive actin polymerization leading to lamellipod extension and cell motility." (PMID 24040362, 2013). "Note, in the context of angiogenesis we found angiopoietin 1 (Angpt1) and tyrosine kinase with immunoglobulin and epidermal growth factor homology domains (TIE1) also down regulated in adenocarcinoma." (PMID 19812696, 2009). "For instance, in adenocarcinoma cells, acute exposure to dexamethasone inhibited epidermal growth factor (EGF)-induced arachidonic acid release, a key inflammation mediator, through a GR-dependent (RU486-sensitive) and transcription-independent (actinomycin D-insensitive) mechanism." (PMID 39769372, 2024). "Moreover, PCI was demonstrated to inhibit in vitro adenocarcinoma cell growth by acting as an epidermal growth factor (EGF) antagonist." (PMID 29495576, 2018). "It was lately discovered that the efficacy of gefitinib was associated with EGF mutations, which is significantly more prevalent in Asian patients with NSCLC, particularly adenocarcinoma, thus explained the discrepancy in the outcome of NSCLC after gefitinib treatment." (PMID 19622166, 2009). "Employing HeLa (adenocarcinoma) cell line as a model system we identified PGE2 and EGF as possible ligands responsible for SP-mediated induction of IL-1α in these neoplastic cells." (PMID 25237386, 2014).
cardiovascular disease (14 papers, 2013 to 2025). "VEGF and EGF may play a role in increased risk of cardiovascular disease in these individuals." (PMID 27145079, 2016). "THBD and KLF2 transcripts, associated with ’Cardiovascular disease’ by IPA analysis, were up-modulated in 2 of 3 EGF-stimulated EOC cells." (PMID 23889749, 2013). "An area for future studies is whether plasma levels of VEGF and EGF are possible mediators of cardiovascular disease in individuals with stress related disorders." (PMID 27145079, 2016). "Moreover, a high-PUFA breakfast may also be adequate since, while its influence on most of the parameters studied was modest, a significant decrease in EGF values was observed, which may be interesting in mitigating the severity of cardiovascular diseases." (PMID 37686743, 2023). "Neuregulin-1β (NRG-1β), a member of the epidermal growth factor (EGF) family, is another antiapoptotic factor that has recently gained attention as a therapy for cardiovascular diseases." (PMID 30949485, 2019).
prostate (11 papers, 1994 to 2025). "Using a human kidney cell model, researchers demonstrated that epidermal growth factor (EGF) was an effective in vitro biomarker of LNA-ASO induced kidney injury." (PMID 35295579, 2022). "In benign and malignant prostate, the overexpression of EGF, bFGF, and IGF protein has been observed." (PMID 34984064, 2021). "Notably, in 2018, Swanton and colleagues reported that, when using fibroblast conditioned media with EGF, the generation rate of the long-term lung tumoroids was 8% due to the overgrowth of normal lung epithelial cells compared to that of lung cancer cells." (PMID 33846488, 2021). "Similarly to SMARCD1, we found that numerous downstream targets of SMARCD2 (e.g., PTGR1, TRMP8, PGC) and SMARCD3 (e.g., EGF, PIK3AP1, HSD3B1) were AR-driven genes that are involved in prostate tumorigenesis, progression and metastasis." (PMID 36611918, 2022). "In the same year, Jang and colleagues reported that they succeeded in culturing long-term lung tumoroids (>10 passages) at a success rate of 70% using media containing FGF2 and EGF but no other growth factors." (PMID 33846488, 2021).
bacterial infection (10 papers, 2012 to 2024). "These include the presence of growth factors, e.g., epidermal growth factor (EGF) and keratinocyte growth factor (KGF), which provide protection against bacterial infections and prevention of water loss." (PMID 38612513, 2024). "Interestingly, enhanced EGF production by HUVECs was abrogated if Bb was killed by fixing with formaldehyde prior to challenge or if a Bb cell lysate was used, suggesting that an active bacterial infection was necessary for increased EGF production." (PMID 32302357, 2020). "Therefore, EGF–Cur-NLC can accelerate wound closure, thus decreasing the risk of bacterial infection." (PMID 33050393, 2020). "The Eudragit RL/RS 100 scaffolds with GS and EGF both showed more rapid wound closure rates as compared to the scaffolds with only GS and without EGF or to the treatment with pure GS ointment, preventing further bacterial infection challenges and promoting the wound healing process." (PMID 30993143, 2019). "When the bacteria infect the host cell, the ALP combines with EGF, thus effecting the EGFR pathway and accelerating bacterial infection of the host cell." (PMID 28184355, 2017). "The role of EGF in hyperproliferation of host cells during a bacterial infection is not commonly described in the literature." (PMID 32302357, 2020).
neurodegenerative disease (8 papers, 2011 to 2024). A disorder of the central nervous system characterized by gradual and progressive loss of neural tissue and neurologic function. "Since 90% of the mutations identified in Notch3 and related to neurodegenerative diseases were located in the EGF region, the mutation analysis was mainly focused on this specific region." (PMID 38790158, 2024). "Given that neuroinflammation may play a causative role in the pathogenesis of neurodegenerative diseases, and many studies have demonstrated mechanistic links among multiple inflammatory pathways in AD, finding a way to reduce EGF may help to counteract some of these mechanisms of action." (PMID 24495355, 2014). "Although the effect of EGF in neurodegenerative disease is well documented in previous reports, the correlation of EGF with DAT in healthy controls has not been investigated yet." (PMID 29038492, 2017). "Treated with appropriate dose of BDNF may significantly improve the effect of EGF-dependent NSPCs to control neurodegenerative diseases or injury." (PMID 22146375, 2011).
metabolic disease (7 papers, 2016 to 2025). A congenital disorder (due to inherited enzyme abnormality) or acquired (due to failure of a metabolically important organ) disorder resulting from an abnormal metabolic process. "STAT3 is a transcription factor that can be activated by IL-6, EGF, and other cytokines, and plays a key role in various biological processes, such as inflammation, cell proliferation, migration, survival, and metabolic disorders." (PMID 27474168, 2016).
inflammation (6 papers, 2014 to 2023). Aberrant reaction of the microcirculation characterized by movement of fluid and leukocytes from the blood into extravascular tissues. "In summary, our results reveal that maternal smoke exposure predisposes dams to exacerbated airway inflammation and offspring to exacerbated immune responses and both phenomena are associated with elevated EGF concentrations." (PMID 34485278, 2021). "In fact, serum EGF levels have been correlated with different patterns of bowel inflammation, epithelial development and wounds in duodenum, which are a reflection of EGF intestinal status." (PMID 37237989, 2023). "Also, IL-31 alone or in combination with IL4 or IL-13 could elevate the expression of epidermal growth factor (EGF), vascular endothelial growth factor (VEGF) and monocyte chemoattractant protein-1 (MCP-1/CCL2) from human bronchial epithelial BEAS-2B cells, which contribute to airway inflammation." (PMID 30647024, 2019).
mental illness (6 papers, 2016 to 2025). "The EGF-related signaling pathways have been previously linked to neurodevelopment, synaptic plasticity, chronic pain, fear, as well as mental health diseases." (PMID 38267423, 2024). "The results of circulating EGF levels studies in mental illnesses are inconclusive." (PMID 34575175, 2021). "The study demonstrated significantly elevated plasma concentrations of vascular endothelial growth factor (VEGF), epidermal growth factor (EGF) and monocyte chemotactic protein-1 (MCP-1) in women with prolonged sick leave due to mild mental illness, clinically diagnosed as exhaustion disorder." (PMID 27145079, 2016). "Moreover, EGF was not related with duration of illness and familial history of mental illness in both groups (P > 0.05)." (PMID 32300175, 2020).
colon (5 papers, 2005 to 2021). "Several signaling pathways, such as Fas/FasL, TNFα/TNF receptor, TRAIL/TRAIL-R, and EGF/EGFR, have been suggested as therapeutic targets to induce apoptosis in gastrointestinal tract cancers." (PMID 19742123, 2009).
intestinal diseases (4 papers, 2017 to 2024). "EGF present in human milk has a protective effect against severe neonatal intestinal diseases, such as NEC, due to its well-known role in altering the balance of pro- and anti-apoptotic proteins." (PMID 30319659, 2018). "Thus, premature infants in the NICU may have multiple sources of vulnerability to intestinal disease: antibiotic-induced dysbiosis, with a lack of dietary EGF, and continued exposure to opportunistic pathogens." (PMID 39042143, 2024).
neurological disease (4 papers, 2021 to 2022). "Similarly, neuregulins, members of the epidermal growth factor (EGF) family, have been linked to altered synaptic function in neurological disease." (PMID 34360985, 2021). "If, by one hand, VEGF and HGF increase vascular permeability contributing to inflammation and nerve damage, and permitting disruption of the blood-brain barrier (BBB), on the other hand, EGF has a neuroprotective role in neurological diseases." (PMID 33776990, 2021). "Indeed, EGF presents a neuroprotective role in neurological disorders." (PMID 33776990, 2021).
myopathy (3 papers, 2020 to 2022). A disease of the muscle in which the muscle fibers do not function properly. "We chose the cytokines bFGF, IFN-γ, EGF and IL-6 that are related to myopathy and or cirrhosis, and found that, bFGF is negatively correlated and the remaining three cytokines are positively correlated to MYO18B mRNA expression." (PMID 32704163, 2020).
brain diseases (2 papers, 2013 to 2015). "The potential contribution of virus-derived cytokines (virokines) that mimic EGF and neuregulin-1 in brain diseases are also discussed." (PMID 23408472, 2013). "CPEC proliferation in response to scratch injury, and its further enhancement by IGF-1/EGF, may have significance in human brain disorders." (PMID 25815836, 2015).
head and neck tumors (2 papers, 2020 to 2021). "The association between serum EGF levels and clinical characteristics of lung- and head and neck tumour patients." (PMID 34115785, 2021). "Overall, there is paucity of data on the levels of expression of epidermal growth factor (EGFR) in head and neck tumors among the African population, particularly in Ghana." (PMID 33273921, 2020). "The results of the present study show that epidermal growth factor influences growth regulation in human head and neck tumors and correlates with prognosis." (PMID 33273921, 2020).
immune diseases (2 papers, 2024 to 2025). "Until such results appear, the decreased serum EGF concentrations may be treated as a surrogate marker of CKD-related immune dysfunction." (PMID 40076962, 2025). "The findings of our study suggest that treatments could be developed for TNFR1-related immune diseases by employing EGF or EGFR agonists in a future clinically valid trial." (PMID 38789573, 2024).
neurodevelopmental disorder (2 papers, 2022 to 2024). A behavioral and cognitive disorder with onset during the developmental period that involves impaired or aberrant development of intellectual, motor, or social functions. "Adding to our evidence, impaired endosomal trafficking of EGF signaling components and Tfn recycling underlie proliferative defects recently identified as a major cause of a neurodevelopmental disorder with microcephaly." (PMID 36369169, 2022). "In conclusion, SPRY2 is an effective regulatory protein of the FGF/VEGF/EGF/BDNF signaling pathway and could be targeted as a therapeutic molecule in neurodevelopmental disorders." (PMID 39456824, 2024).
respiratory diseases (2 papers, 2019 to 2022). "EGF has been identified as a factor associated with lung growth and respiratory diseases since its discovery in the early 1960s; however, there is a lack of knowledge of whether EGF in amniotic fluid may be a predictive biomarker of respiratory outcomes in preterm neonates." (PMID 35328399, 2022). "Although EGF appears to have a considerable impact on normal lung maturation and the development of respiratory diseases of prematurity such as RDS and BPD, little has been done to evaluate EGF as a predictor of neonatal outcomes." (PMID 35328399, 2022). "In animal models, intraamniotic EGF injections decrease the severity and duration of respiratory disease in preterm newborns." (PMID 35328399, 2022). "Among them, representative respiratory diseases-related targets included IL-6, IL-10, IL-1β, TNF-α, interferon (IFN)-γ, epidermal growth factor (EGF) and its receptor (EGFR), TNF-α, transforming growth factor (TGF)-β1, etc." (PMID 31530860, 2019).
benign tumours (1 paper, 1996). "Finally, 33% (5/15) of the benign tumours expressed EGF receptor mRNA, whereas 40% (6/15) expressed EGF mRNA and 7% (1/15) expressed TGF-alpha mRNA." (PMID 8562334, 1996).
hematological cancers (1 paper, 2024). "Particularly controversial is the increased concentration of various growth factors, such as PDGF, EGF, VEGF and Angiopoietin-1, whose role in the pathogenesis of hematological cancers is clearly negative." (PMID 38673624, 2024).
Muscular Disorders (1 paper, 2022). "Under EGF stimulated conditions, one of the top network related to RSK1 KO-specific DEGs was “Cellular Development, Cellular Movement, Skeletal and Muscular Disorders”." (PMID 36684450, 2022).
EGF also shares sentences with these, for which no sentence is quoted: ovarian tumor (9 papers); ischemic stroke (7); multiple myeloma (4); polycystic ovary syndrome (4); gliosarcoma (3); hepatitis C (3); Huntington disease (3); lung disease (3); metastasis (3); metastatic melanoma (3); neuropathy (3); renal cysts (3); urothelial cell carcinoma (3); acute respiratory distress syndrome (2); alcohol abuse (2); allergies (2); anal carcinoma (2); anaplastic astrocytoma (2); aortic aneurysm (2); autism spectrum disorder (2); binge eating disorder (2); Cestode Infections (2); chronic gastritis (2); chronic rhinosinusitis (2); colon adenoma (2); dental caries (2); dysplasia (2); EAST syndrome (2); end-stage renal disease (2); Gitelman syndrome (2).
A further 194 diseases each share a sentence with EGF in 2 papers or fewer.